RHOXF2 (Rhox homeobox family member 2)
Description:
Transcription factor maybe involved in reproductive processes. Modulates expression of target genes encoding proteins involved in processes relevant to spermatogenesis.
Synonyms: PEPP2; THG1; PEPP-2; CT107
Tractability: Antibody: the Human Protein Atlas places it where antibodies can reach.
Gene: Protein-coding gene on chromosome X (120,158,613 to 120,165,630, forward strand). Ensembl gene ENSG00000131721.
Subcellular location: Nucleus
Subcellular location (Human Protein Atlas): Plasma membrane; Nucleoplasm
Gene Ontology:
Molecular function: identical protein binding; protein binding; sequence-specific double-stranded DNA binding; DNA-binding transcription factor activity, RNA polymerase II-specific; RNA polymerase II transcription regulatory region sequence-specific DNA binding; DNA binding
Biological process: positive regulation of gene expression; neuron development; regulation of transcription by RNA polymerase II; regulation of DNA-templated transcription
Cellular component: chromatin; nucleus
Homologues: Orthologues: macaque RHOXF2 (78% identical). Paralogues in human: RHOXF2B (99% identical), ARX (19% identical), PAX7 (18% identical), ESX1 (18% identical), RHOXF1 (18% identical), PAX3 (17% identical), PRRX2 (17% identical), PITX1 (16% identical), PRRX1 (16% identical), UNCX (16% identical), OTP (16% identical), PAX6 (16% identical), and 38 more.
Diseases named in the same sentence as RHOXF2 in open-access papers:
RHOXF2 is named in the same sentence as 18 diseases in open-access papers, as found by Europe PMC text mining. Sharing a sentence is not in itself a finding about the gene and the disease. The quoted sentences say what the papers report.
Azoospermia (1 paper, 2014). Absence of any measurable level of sperm,whereby spermatozoa cannot be observed even after centrifugation of the semen pellet. "First, all four RHOXF2 exons were sequenced in 47 patients with oligospermia or non-obstructive azoospermia." (PMID 25780578, 2014). "The four exons in each of RHOXF2 and RHOXF2B were sequenced in 47 patients with oligospermia or non-obstructive azoospermia." (PMID 25780578, 2014).
breast adenocarcinoma (1 paper, 2014). "We then tested if RHOXF2 overexpression could confer resistance to the rtTA-expressing human breast adenocarcinoma cell line MCF7_M2 and the adenocarcinomic human alveolar basal epithelial cell line A549_M2." (PMID 24944581, 2014).
breast carcinoma (1 paper, 2015). "ODF4 and RHOXF2 expressions were detectedin 62.5 and 60% of breast cancer tissues but alsoin 22.5 and 17.5% of normal tissues examinedrespectively." (PMID 26464818, 2015). "ODF4 and RHOXF2 are proposed as putative breast cancer biomarkersat the transcript level." (PMID 26464818, 2015). "Considering the roleof RHOXF2 cell transformation and cell tocell contacts, in addition to its up-regulationin breast cancer tissues (the present study), it mayparticipate in the process of tumorigenesis." (PMID 26464818, 2015).
Fibroadenoma (1 paper, 2015). A benign tumor of the breast characterized by the presence of stromal and epithelial elements. "ACRBP, ODF4 and RHOXF2 were expressedin 60, 10 and 10% of fibroadenomas respectively.None of the fibroadenoma samples showed SPATA19expression." (PMID 26464818, 2015).
leukemia (1 paper, 2014). A malignant (clonal) hematologic disorder, involving hematopoietic stem cells and characterized by the presence of primitive or atypical myeloid or lymphoid cells in the bone marrow and the blood. "Interestingly, although no growth disadvantage was observed in K562 cells partially depleted for RHOXF2, its depletion via shRNA increased the sensitivity of this leukemia cell line to several pharmacological compounds." (PMID 24944581, 2014).
male infertility (1 paper, 2014). The inability of the male to effect fertilization of an ovum after a specified period of unprotected intercourse. "The objective of the present study was to test for the involvement of RHOXF2 genes in male infertility of secretory origin." (PMID 25780578, 2014). "Mutations in the RHOXF2 and RHOXF2B genes (which encode homeodomain proteins exclusively expressed in the testis) might explain some cases of male infertility." (PMID 25780578, 2014).
testicular cancer (1 paper, 2014). A primary or metastatic malignant neoplasm that affects the testis. "Computational analysis predicts RHOXF2 to be a testicular cancer candidate gene and, in fact, the transcript was detected in several types of human testicular cancers." (PMID 24944581, 2014).
cancer (5 papers, 2011 to 2024). A tumor composed of atypical neoplastic, often pleomorphic cells that invade other tissues. "Mechanistically, RHOXF2 promotes cancer cell proliferation and invasion by regulating key signaling pathways, including the Wnt2/β-catenin pathway, which is involved in tumor progression." (PMID 39136001, 2024). "LOXL1-AS1 acts as a sponge that targets miR-3128 to promote RHOXF2 expression, thereby promoting metastasis of this type of cancer cells." (PMID 39136001, 2024). "A genome-wide analysis of cancer-testis (CT) gene expression showed that RHOXF2 is a CT gene with testis-selective expression." (PMID 21988730, 2011). "The RHOXF2 protein is a member of the RHOX family of homeobox genes, which encode transcription factors involved in regulating the expression of genes related to the development of cancer." (PMID 39136001, 2024). "RHOXF2 is a CTA expressedin a wide variety of cancer cell lines and tumorsamples." (PMID 26464818, 2015). "Therefore, we asked if sensitivity to DNA damaging agents was observed when RHOXF2 is knocked down in cancer cells where the protein is normally expressed." (PMID 24944581, 2014). "Furthermore, RHOXF2 protein expression was detected in several cancer cell lines." (PMID 24944581, 2014).
RHOXF2 also shares sentences with these, for which no sentence is quoted: chondrosarcoma (1 paper); chronic myelogenous leukemia (1); ductal carcinoma (1); Infertility (1); ischemic stroke (1); multiple myeloma (1); non-small cell lung carcinoma (1); nonsmall cell lung cancer (1); oligospermia (1); thyroid gland medullary carcinoma (1).